FOXP3 (forkhead box P3)
Diseases named in the same sentence as FOXP3 in open-access papers (continued):
Sharing a sentence is not in itself a finding about the gene and the disease.
non-Hodgkin lymphoma (5 papers, 2014 to 2025). Distinct from Hodgkin lymphoma both morphologically and biologically, non-Hodgkin lymphoma (NHL) is characterized by the absence of Reed-Sternberg cells, can occur at any age, and usually presents as a localized or generalized lymphadenopathy associated with fever and weight loss. "Early clinical investigations employing IL-2 as an adjuvant for CAR T cell therapy in non-Hodgkin lymphoma demonstrated an increase in the frequency of FOXP3+ Treg cells." (PMID 39697333, 2024). "In HIV-positive individuals at risk for developing non-Hodgkin lymphoma (pre-NHL), CD8+PD-1+CD27+CXCR4− T-cells positively correlate with CD4+FoxP3+PD-1+ T-cells expressing CD27, CD28, ICOS, and CD71." (PMID 41148820, 2025). "T cells expressing FOXP3 and Helios were documented in the fine needle aspirates of affected lymph nodes of dogs with spontaneous multicentric B cell lymphoma (BCL), proposed to be a model for human non-Hodgkin lymphoma." (PMID 25119018, 2014).
Opportunistic infection (5 papers, 2010 to 2023). An infection that is caused by a pathogen that would generally not be able to cause an infection in a host with a normal immune system. "It has been demonstrated that the strong suppressive activity of the TIGIT+FOXP3+T regulatory cells subset on cellular immunity predisposes septic individuals to acquire opportunistic infections due to the development of immunosuppression." (PMID 37604833, 2023). "The finding of increased percentages of CD4+ T cells expressing FOXP3 in HIV infected individuals suggests that an imbalance of regulatory to effector T cells could be responsible for susceptibility to opportunistic infection." (PMID 20668701, 2010). "The TIGIT+FOXP3+Treg subset (TIGIT+Tregs) exerts robust suppressive activity on cellular immunity and predisposes septic individuals to opportunistic infection." (PMID 37604833, 2023). "This increase of immunoregulatory CD4+CD25+FoxP3+ T-cells (Treg) during chronic HIV infection disables the immune system’s control over viral replication as well as opportunistic infections." (PMID 22859956, 2012). "In both of our patients, the regulatory CD4+CD25+ T cell subset was significantly increased when opportunistic infections occurred, although we did not examine Foxp3 expression." (PMID 26693362, 2015).
oral lichen planus (5 papers, 2021 to 2022). Oral lichen planus is a chronic inflammatory oral condition of unknown aetiology characterized by T-cell-mediated chronic immune response and abnormal epithelial keratinization cycle. "In 2019, Wang et al26 found that overexpression of the lncRNA DQ786243 in functional FOXP3+ Treg cells provides a novel benefit for oral lichen planus (OLP), including autoimmune and inflammatory diseases." (PMID 35266286, 2022). "Also, other signaling pathways including microRNA-155-IFN-γ loop and FOXP3/miR-146a/TRAF6 pathways were reported to be involved in the pathogenesis of oral lichen planus." (PMID 34670484, 2021). "The FOXP3/miR-146a/NF-κB axis was previously reported to modulate the induction and function of CD4+ Treg cells to alleviate oral lichen planus." (PMID 34670484, 2021). "In the precancerous condition of oral lichen planus (OLP) and precancerous lesion actinic cheilitis (AC), FOXP3+ cell infiltration increased, and CD8+/FOXP3+ cell ratio decreased, suggesting the promoting role of Treg in cancer progression." (PMID 34177907, 2021). "Significantly higher numbers of Foxp3+ cells were detected in both CHC and oral lichen planus compared to SqP (Dunn’s post hoc test, connective tissue: ρ = 0.011 for CHC vs. SqP and p < 0.001 for LP vs. SqP; Dunn’s post hoc test, epithelium: p = 0.003 for CHC vs. SqP and ρ < 0.001 for LP vs. SqP)." (PMID 34209407, 2021). "The FOXP3/miR-146a/NF-κB axis was previously reported to modulate the induction and function of CD4+ Treg cells to alleviate oral lichen planus, while other signaling pathways including microRNA-155-IFN-γ loop and FOXP3/miR-146a/TRAF6 pathways are involved in the pathogenesis of oral lichen planus." (PMID 34670484, 2021).
oropharyngeal squamous cell carcinoma (5 papers, 2014 to 2025). "For example, increased infiltration of CD3+, CD4+, CD8+, FoxP3+, CD20+ and CD56dim was detected in patients with oropharyngeal squamous cell carcinoma and was associated with improved overall survival." (PMID 34823553, 2021).
peanut allergy (5 papers, 2015 to 2023). "In patients with peanut allergy the treatment with oral immunotherapy resulted in increased antigen‐driven Treg function and hypomethylation of Foxp3." (PMID 35344298, 2022).
relapsing-remitting MS (5 papers, 2012 to 2017). "Decrease in the number of CD4+Foxp3+ T cells as well as the expression level of Foxp3 is becoming an important characteristic of relapsing-remitting MS and other lymphoproliferative autoimmune disorders." (PMID 28367355, 2017). "It has been shown that there is a significant decrease in the number of CD4+Foxp3+ T cells as well as the expression level of Foxp3 in relapsing-remitting MS and other lymphoproliferative autoimmune disorders." (PMID 23284794, 2012). "Also, expression of Foxp3 and levels of visfatin in relapsing remitting-MS(RR-MS) patients were higher compared with the other subgroups." (PMID 24098530, 2013).
small cell lung carcinoma (5 papers, 2016 to 2024). Small cell lung cancer (SCLC) is a highly aggressive malignant neoplasm, accounting for 10-15% of lung cancer cases, characterized byrapid growth, and early metastasis. "FOXP3 has been shown to promote EMT in non–small cell lung cancer cells through a Wnt/β-catenin pathway." (PMID 39099201, 2024). "In small cell lung cancer, relapse- free survival in patients with Foxp3-positive tumor was better with earlier follow-up." (PMID 27457382, 2016). "In a cohort of 32 small cell lung cancer (SCLC) BrM specimens, a dense accumulation of CD3+, CD8+, and CD45RO+ T cells in the perivascular area was observed, while FOXP3+ TILs were more abundant within the tumor area and less within the perivascular area." (PMID 31824260, 2019).
steatosis (5 papers, 2021 to 2025). Increased lipid within the cytoplasm of cells. "Similarly, the livers in the HFD-fed Blimp-1fl/fl Foxp3-Cre+ mice were smaller and less pale, suggesting reduced steatosis relative to their WT counterparts." (PMID 33351782, 2021). "All four CD4+ T cell subsets, T-bet+ (Th1), Eomes+ (cytotoxic), FoxP3+ (Tregs), and RORγt+ (Th17), were elevated in MASH livers compared to isolated steatosis, with T-bet+ CD4+ T cells showing a statistically significant increase." (PMID 40631180, 2025). "Liver sections from patients with isolated steatosis or MASH were stained with a panel of antibodies against select T-cell markers, including T-bet, Eomes, FoxP3, and RORγt." (PMID 40631180, 2025). "Several parameters distinguished patients with simple steatosis at the early MASLD stage from those with steatosis with inflammation – advanced MASLD, including Foxp3+ [% of CD4+CD25+]; IL-10 [MFI in CD4+ and CD4+CD25+ populations]." (PMID 40918132, 2025). "Nevertheless, it is interesting to mention that IL-17A+ cells were absent in cases with mild steatosis with its consequent impact on the IL-17A+/Foxp3+ cell ratio." (PMID 33664397, 2021). "Most remarkable, only those severe cases displayed Foxp3+ and IL-17A+ cells; one possible explanation for this observation could be that CD4+ lymphocyte frequency is very low in steatosis grade 1 and 2 cases, therefore these subpopulations may be underrepresented in these stages." (PMID 33664397, 2021). "Furthermore, the iWAT and livers, but not the epididymal VAT, were smaller in the IL-10fl/fl Foxp3-Cre+ mice, and the livers appeared smaller and less pale, suggesting protection from hepatic steatosis." (PMID 33351782, 2021).
tetanus (5 papers, 2012 to 2025). A serious infectious disorder that follows wound contamination by the Gram-positive bacterium Clostridium tetani. "In fact, in another long-term study, when human T cells, co-cultured with the other PBMC, were activated with the tetanus antigen plus IL-2, dexamethasone (10−7 M) decreased the levels of FoxP3 mRNA following long-term culture (11 days)." (PMID 30845709, 2019). "However, a population of antigen-responsive Treg cells is still detected, as evidenced by quantifying OX40+CD25+ Foxp3+Helios+ Treg cells in response to tetanus peptide pool stimulation." (PMID 29065175, 2017). "Herein, we explore the role of CD4+FOXP3+CD127− Tregs in controlling immunity in infant males and females to vaccination with diphtheria–tetanus–whole cell pertussis (DTP) and/or measles vaccine (MV)." (PMID 28855899, 2017).
tongue cancer (5 papers, 2018 to 2025). A malignant neoplasm affecting the tongue. "It is critical to emphasize that FOXP3 is expressed in both immune and tumor cells, as demonstrated in multiple cancer types, including tongue carcinoma." (PMID 40806346, 2025).
vasculitis (5 papers, 2011 to 2022). "In anti‐neutrophil cytoplasmic autoantibody (ANCA) vasculitis, Tregs possess diminished suppressive capacity, which has been attributed to the expression of a FOXP3 splice‐variant lacking exon 2 in T cells (FOXP3Δ2 CD4+ T cells)." (PMID 36381498, 2022). "Accordingly, patients suffering from systemic vasculitis with renal involvement had a significantly lower expression of CD122 on Tregs when compared to patients with localized, nonrenal vasculitis (CD4+CD25+FoxP3+ Tregs: %CD122+ 34 ± 19% versus 49 ± 10%, P = 0.04)." (PMID 24648606, 2014).
acute T cell leukemia (4 papers, 2017 to 2025). "However, an in vitro study demonstrated that overexpression of miR-182 in Jurkat T cells, a CD4+ cell line derived from human acute T cell leukemia, downregulated Foxo1 expression and promoted the polarization of the transduced T cells to Foxp3+ T cells, of which some were Foxp3+IL-17+ cells." (PMID 36891312, 2023). "However, the role of FOXP3 in acute T-lymphoblastic leukemia (T-ALL) cells is not known." (PMID 30103821, 2018).
autoimmune encephalitis (4 papers, 2021 to 2025). Inflammation of the brain secondary to an immune response triggered by the body itself. "For Blimp-1+ eTregs in the CNS of experimental autoimmune encephalitis-diseased animals it was elucidated that Blimp-1, here maintained by proinflammatory STAT-1 signaling, ensures Foxp3 expression by inhibition of the methyltransferase Dnmt3a." (PMID 35069572, 2021). "In an experimental autoimmune encephalitis (EAE) model, C-PC decreased disease severity and upregulated key markers of regulatory T cells—FOXP3, CD25, IL-10, and TGF-β—while simultaneously exerting neuroprotective effects that mitigated myelin and axonal damage." (PMID 41514979, 2025). "Central Nervous System (CNS) Foxp3+ TREG cells also express Blimp1, and mice with a conditional deletion of Blimp1 in Foxp3+ TREG cells displayed a significant reduction in IL-10 production and increased disease severity upon experimental autoimmunity encephalitis (EAE) induction." (PMID 35154079, 2021).
Cachexia (4 papers, 2016 to 2021). Severe weight loss, wasting of muscle, loss of appetite, and general debility related to a chronic disease. "In addition to the cachexia-associated loss of CD3+ T cells, this analysis demonstrated the depletion of CD8+ T cells, CD4+Foxp3− T cells, and NK cells." (PMID 27829137, 2016). "Regarding the NSCL cancer patients, significantly lower serum levels of SOCS1 and Foxp3 were noted in cachexia as compared with non-cachexia." (PMID 34900737, 2021).
cervical squamous cell carcinoma (4 papers, 2017 to 2026). A squamous cell carcinoma arising from the cervical epithelium. "Immunohistochemistry and immunofluorescence staining were used to detect B7-H4, Foxp3, CD4, CD8, and interferon-γ in the 75 pairs of specimens obtained via biopsy; 20 samples were found to have chronic cervicitis, and another 20 had squamous cell carcinoma of the cervix." (PMID 34651047, 2021).
chronic gastritis (4 papers, 2012 to 2025). Inflammation of the stomach that is chronic in nature. "Besides, this study proved that IL22+ CD4+ T cells and Foxp3+ Treg cells were positively correlated with H. pylori colonization and the severity of chronic gastritis." (PMID 36705412, 2023). "The median number of FOXP3+ infiltrating cells was higher (27 cells/cm2) in gastric MALT patients than in DLBCL (10 cells; p = 0.162) but similar to chronic gastritis (20 cells; p = 0.605)." (PMID 23284739, 2012). "The proportion of FOXP3+ as a fraction of all CD3+ cells was not different between MALT lymphoma and DLBCL or chronic gastritis (p = 0.826 and p = 0.222, respectively)." (PMID 23284739, 2012).
chronic kidney disease (4 papers, 2021 to 2024). Impairment of the renal function secondary to chronic kidney damage persisting for three or more months. "Our study provides some evidence of T-cell dysfunction in the pathology of kidney injury in acute and chronic kidney disease via activity of Foxp3 and RORγt." (PMID 34868786, 2021). "Our study favours the hypothesis of the role of T-cell dysfunction in kidney injury (acute and chronic kidney disease) via activity of Foxp3 and RORγt." (PMID 34868786, 2021). "Thus, the consequences of end stage renal disease may have altered FOXP3 pre-mRNA and mature mRNA levels." (PMID 38802392, 2024). "The frequent occurrence of FOXP3+ Tregs in fibrotic areas of interstitial tissue leads to the question of whether the development of chronic kidney disease (CKD) and chronic interstitial fibrosis (independent of the initial immunological cause) precedes FOXP3+ Tregs' presentation." (PMID 34336285, 2021).
cognitive decline (4 papers, 2015 to 2024). "The transient depletion of Foxp3+ Tregs, or the pharmacological inhibition of their activity, leads to Abeta plaque clearance, a reduction in the neuroinflammatory response, and a reversal of cognitive decline." (PMID 39226167, 2024). "Here we show, using the 5XFAD AD mouse model, that transient depletion of Foxp3+ regulatory T cells (Tregs), or pharmacological inhibition of their activity, is followed by amyloid-β plaque clearance, mitigation of the neuroinflammatory response and reversal of cognitive decline." (PMID 26284939, 2015).
demyelinating disease (4 papers, 2012 to 2021). A broad group of disorders that affect the myelin sheaths that cover the neurons. "Thus, the potential function of virus-specific FoxP3+CD4+ T cells accumulated in the CNS of susceptible mice early after TMEV infection may contribute to the pathogenesis of TMEV-induced demyelinating disease." (PMID 33086489, 2020). "FoxP3+ regulatory cells are known to play an important role in the pathogenesis of TMEV-induced demyelinating disease." (PMID 28445497, 2017). "As virus-reactive IFN-γ-producing Th1 cells are protective but IL-17-producing Th17 cells inhibit Th1 development and cytotoxic T cell function, FoxP3+CD4+ T cells together with Th17 cells may promote the pathogenesis of TMEV-induced demyelinating disease in an epitope-dependent manner." (PMID 34067536, 2021). "Because virus-reactive IFN-γ-producing Th1 cells are protective, but IL-17-producing Th17 cells are known to inhibit Th1 development and cytotoxic T cell functions, FoxP3+CD4+ T cells, together with Th17 cells, may promote the pathogenesis of TMEV-induced demyelinating disease." (PMID 33086489, 2020). "Recently, it was also shown that the presence of FoxP3+ Treg cells that preferentially expand due to stimulation by IL-1β is not beneficial for the development of TMEV-induced demyelinating disease; hence, these regulatory cells inhibit the protective anti-viral immune responses." (PMID 22985464, 2012).
dry eye (4 papers, 2017 to 2023). "Previous studies further demonstrated that the numbers of CD4+CD25+FoxP3+Tregs play a crucial role in the pathology of dry eye." (PMID 28091781, 2017). "SS dry eye and non-SS dry eye human-delivered FMT transplanted into germ-free C57BL/6J female mice resulted in decreased corneal barrier integrity and decreased concentrations of CD45+ CD4+ FOXP3+ in cervical lymph node cells, indicating that Treg cells could modulate gut microbiome or vice versa." (PMID 36142642, 2022).
encephalomyelitis (4 papers, 2013 to 2025). Inflammation of the brain and the spinal cord. "In the current study, VD3-liposome-treated skin DCs induced FoxP3+ T cells in coculture, aligning with results of our previous study utilizing soluble VD3 for intradermal injection, as well as, with in vivo findings in a rat model of encephalomyelitis." (PMID 40791842, 2025).
gingivitis (4 papers, 2019 to 2021). A disorder involving inflammation of the gums; may affect surrounding and supporting structures of the teeth. "Analysis of CD4+IL-17A+Th17/CD4+CD25+Foxp3+Treg cells revealed a higher ratio in the gingivitis group, relative to healthy controls." (PMID 34234776, 2021). "Similarly, specific transcription factors Foxp3 (of Treg) and RORγt (of Th17) were upregulated in gingivitis patients, relative to healthy controls, although only RORγt was statistically different between the group." (PMID 34234776, 2021). "Similarly, Foxp3 and RORγt also exhibited an increasing growing trend in the gingivitis group." (PMID 34234776, 2021). "Significantly, IL-17A+ Foxp3+ T cells are also found in human periodontal lesions but not in gingivitis." (PMID 32391008, 2020). "Taken together, a possible mechanism of gingivitis is that an increase in TGF-β content, coupled with IL-10 upregulation, in peripheral blood lymphocytes activated Treg cells, while transcription factor Foxp3 participated in a synergistic effect, thereby producing CD4+CD25+Foxp3+Treg cells." (PMID 34234776, 2021).
hemophilia (4 papers, 2013 to 2023). Hemophilia is a genetic disorder characterized by spontaneous hemorrhage or prolonged bleeding due to factor VIII or IX deficiency. "Of these subsets, FoxP3+ Tregs have been the most extensively studied in hemophilia." (PMID 30842776, 2019). "Thus, we investigated whether FoxP3+ Tregs isolated from inhibitors-positive haemophilia B mice after gene therapy acquired in vivo FIX-specific suppressive capacity." (PMID 24106222, 2013). "Employing murine models of the inherited bleeding disorder hemophilia, we find that oral antigen administration induces three CD4+ Treg subsets, namely FoxP3+LAP-, FoxP3+LAP+, and FoxP3-LAP+." (PMID 37954612, 2023).
idiopathic pulmonary fibrosis (4 papers, 2018 to 2025). Idiopathic pulmonary fibrosis (IPF) is a nonneoplastic pulmonary disease that is characterized by the formation of scar tissue within the lungs in the absence of any known cause. "In support of these observations, Shimizu and colleagues showed that interstitial Foxp3-positive lymphocytes decreased in the lungs of patients with usual interstitial pneumonia." (PMID 29690905, 2018).
ischemic stroke (4 papers, 2021 to 2025). A stroke disorder caused by obstruction of blood flow to the brain, due to thrombotic (local blood clot formation) or embolic (due to a blood clot or other material traveling from another site) event. "This undetermined population of CD45+ cells retains myeloid features and is similar in phenotype to a subpopulation of F4/80+/FoxP3+ macrophages reported to infiltrate lesions resulting from ischemic stroke." (PMID 38053333, 2024).